SUMO2P1 (SUMO2 pseudogene 1)
Synonyms: SMT3Bp; dJ271M21; formerly SMT3H2P; SUMO2P
Gene: Transcribed processed pseudogene on chromosome 6 (29,636,060 to 29,636,343, reverse strand). Ensembl gene ENSG00000235238.
Diseases named in the same sentence as SUMO2P1 in open-access papers:
SUMO2P1 is named in the same sentence as 2 diseases in open-access papers, as found by Europe PMC text mining. Sharing a sentence is not in itself a finding about the gene and the disease.
SUMO2P1 shares sentences with these, for which no sentence is quoted: sarcoidosis (1 paper); Sepsis (1).